NEAT1 (nuclear paraspeckle assembly transcript 1)
Diseases named in the same sentence as NEAT1 in open-access papers (continued):
Sharing a sentence is not in itself a finding about the gene and the disease.
cancer (continued). "Recently, the levels of NEAT1 are reported to be dynamically regulated in different cancer types." (PMID 27075229, 2016). "NEAT1 dysregulation facilitates tumorigenesis in a variety of human cancers." (PMID 27270317, 2016). "This discrepancy might be explained by the different expression pattern of mRNAs that were influenced by NEAT1 in various types of cancer." (PMID 26911892, 2016). "Certainly, further studies will be needed to determine the oncogenic mechanism of NEAT1 in cancer." (PMID 26314847, 2015). "Considering that cancer cells have altered mechanisms for nucleoplasmic mRNA transport, it is possible that NEAT1 may play a role in regulating this pathway in cancer." (PMID 23976967, 2013). "Therefore, Neat1 expression varies significantly across different cancer types." (PMID 40027195, 2025). "Therefore, the regulation of NEAT1 on cancer chemotherapy resistance may be achieved through these pathways." (PMID 38970092, 2024). "TUG1, NEAT1,HOTAIR, and CCAT1are examples of lncRNAs that might potentially cause cancer." (PMID 39512820, 2024). "In addition, further studies are needed to determine whether the expression of lncRNA NEAT1 in various cancers is specific, and whether other factors are involved in the expression process and how the expression is affected." (PMID 39139172, 2024). "Therefore, in-depth study of the specific molecular regulation mechanism of NEAT1 in cancer chemotherapy resistance is of great value for screening effective and potential new targets for cancer chemotherapy sensitization, and provides new ideas and new directions for cancer chemotherapy." (PMID 38970092, 2024). "Furthermore, it is imperative to delve into the mechanisms responsible for the elevation of NEAT1 in cancers, whether through transcriptional activation or alterations in stability." (PMID 38343745, 2024). "Clearly, NEAT1 may be an important potential biomarker and clinical therapeutic target for cancer." (PMID 39139172, 2024). "Preliminary clinical data show that higher NEAT1 and MALAT1 expressions correlate with reduced A3B and increased A3A activities in cancers like breast and lung, suggesting their role in enzymatic balance between A3B and A3A, affecting mutation dynamics and cancer progression." (PMID 39322638, 2024). "In addition, whether NEAT1 isoforms are also differentially dysregulated in other types of cancers and brain diseases warrants rigorous reinvestigation." (PMID 39032650, 2024). "However, there is controversy about the oncogenic or tumor suppressor function of NEAT1 in cancer." (PMID 37706018, 2023). "Thus, considering the roles of NEAT1 in cancer promotion, chemoresistance, and cancer stemness, it was suggested that it could be used as a new clinical therapeutic target for treating TNBC patients." (PMID 37795578, 2023). "Whereas, how the effect of NEAT1 was delivered to cancer cells remains unclear." (PMID 36762032, 2023). "Thus, the induction of NEAT1_2 is regarded as tumour suppressive, whereas high levels of NEAT1_1 have oncogenic consequences, suggesting that NEAT1 may have a dual role in cancer formation." (PMID 35457249, 2022). "Elucidating the molecular interaction of NEAT1 may shed light on future treatment of cancer." (PMID 36011001, 2022). "Hence, elucidating the molecular interaction of NEAT1 may shed light on the future treatment of cancer." (PMID 36011001, 2022). "In addition, NEAT1, a lncRNA, is known to be an oncogenic molecule in various cancers." (PMID 36050752, 2022). "NEAT1 might influence the radiosensitivity of various cancer cells including HCC." (PMID 35054896, 2022). "In some haematological malignancies, NEAT1 functions as a tumour suppressor, enhancing the expression of NEAT1_2, and thus paraspeckle formation, which may counteract oncogene-induced stressors in cancer." (PMID 36139550, 2022).
cancer (continued). "Besides this architectural role, NEAT1 showed to be involved in various processes related to cancer, such as invasion, migration, proliferation, DNA damage, etc., but the concrete tumorigenesis mechanism of NEAT1 remains unclear." (PMID 33917553, 2021). "This discrepancy might be attributed to the dual role of NEAT1 in cancer development." (PMID 33670447, 2021). "Therefore, targeting the feedback loop of NEAT1/miRNA/target may be a potential pathway to overcome therapeutic resistance in cancer." (PMID 34512157, 2021). "Finally, six lncRNAs (DLEU2, HOTTIP, MALAT1, NEAT1, SNHG1, and TUG1), registered in Lnc2Cancer 2.0, a database offering comprehensive experimentally supported associations between lncRNA and human cancer, were selected as candidate lncRNAs for the diagnosis of HCC." (PMID 34185961, 2021). "It indicated that m6A in NEAT1–1 may exhibit oncogenic function in cancer progression." (PMID 33308223, 2020). "To further study the m6A modification of NEAT1–1 in a clinicopathologically relevant context, we harvest the RNA immunoprecipitated by m6A antibody from fresh sample of adjacent normal cancer, primary cancer, lymph node-metastasis cancer and bone-metastatic cancer." (PMID 33308223, 2020). "In addition, Neat1 can enhance or suppress cancer progression in a condition-specific manner." (PMID 31822595, 2020). "According to lnc2Cancer, the most studied cancer-associated lncRNAs are MALAT1, H19, HOX antisense intergenic RNA (HOTAIR), maternally expressed 3 (MEG3), taurine upregulated 1 (TUG1), antisense non-coding RNA in the INK4 locus (ANRIL) and nuclear-enriched abundant transcript 1 (NEAT1)." (PMID 32340118, 2020). "However, the underlying mechanism is still elusive.Combing with our findings, it is suggested that NEAT1-mediated miRNA down-regulation might be a common mechanism for abnormal miRNA expression in human cancers." (PMID 31344855, 2019). "Although these cancer entities are completely different regarding their localization, progression, molecular, and cellular features, they have one thing in common, that is, the NEAT1 phenotype namely (a) highly increased NEAT1 levels in tumor tissue and cancer cell lines." (PMID 30430751, 2019). "Nuclear paraspeckle assembly transcript 1 (NEAT1) and metastasis-associated lung adenocarcinoma transcript 1 (MALAT1), also known as Nuclear-Enriched Abundant Transcript 2 (NEAT2) were among the first lncRNAs to be implicated in progression and metastasization of cancers." (PMID 31003545, 2019). "Thus, authors propose that NEAT1 knockdown might repress cancer cell growth via miR‐101‐dependent EZH2 regulation." (PMID 30430751, 2019). "Thus, HuR inhibition may offer new conceptual routes to treat cancers expressing high levels of NEAT1." (PMID 30374364, 2018). "The compositions of NEAT1 isoforms may vary in different cancer types." (PMID 30374364, 2018). "However, its expression was reduced in acute promyelocytic leukemia, indicating that the role of NEAT1 may vary with cancer types." (PMID 30374364, 2018). "However, the effect of NEAT1 on the outcome of cancer patients has been controversial." (PMID 28507281, 2017). "However, the upstream mechanisms of NEAT1 overexpression in cancers await to be uncovered." (PMID 28615056, 2017). "Therefore, NEAT1 expression level may be an indicator of the intrinsic characteristics of cancer progression." (PMID 28507281, 2017).
cancer (continued). "These indicate that overexpression of NEAT1 lncRNA in GAC might mainly regulate the genes that correlated with cell growth but not the genes associated with cancer metastasis." (PMID 26911892, 2016). "Therefore, its regulation in cancer along with the development of new therapeutic targets of NEAT1 may represent promising tools against OC therapy." (PMID 27075229, 2016). "In the current study, we identified 24 differentially expressed lncRNAs in NPC including GAS5, NEAT1 and H19, which contribute to the development and progression of cancers and might serve as novel, non-invasive biomarkers for cancer diagnosis, progression and prognosis." (PMID 26246469, 2015). "Hypoxia in tumors can induce the transcription of NEAT1 and paraspeckle formation in a HIF-2α-dependent manner, leading to cancer cell survival." (PMID 40362651, 2025). "Key lncRNAs, including HOTAIR, H19, NEAT1, LINC00511, and FMR1-AS1, have been recognized as central components of the regulatory hierarchy governing cancer stem-cell properties." (PMID 41373831, 2025). "Suppressing lncRNAs such as NEAT1, MALAT1, and UCA1 through various methods including CRISPR/Cas9, siRNA, or antisense oligonucleotides has been shown to impede cancer development." (PMID 39941858, 2025). "In many different kinds of human cancer, NEAT1 is the nuclear-enriched abundant transcript 1 (NEAT1) lncRNA." (PMID 41244835, 2025). "Elevated NEAT1 and MALAT1 levels correlate with A3B activity modulation, indicating their potential as biomarkers for monitoring A3B enzymatic activity in cancer." (PMID 39322638, 2024). "NEAT1 and MALAT1 non-coding lncRNAs and their protein-binding partners are frequently overexpressed to similar level in different cancer types." (PMID 39322638, 2024). "The binding of miR-483 with NEAT1 increased STAT1, STAT3 and other EMT markers in U2O3 cells and greatly helped in EMT and metastasis of cancer cells." (PMID 40176927, 2024). "Research has shown that STING is highly expressed in cancer tissues, and DNMT1 can mediate STING inhibition by interacting with nuclear paraspeckle assembly transcript 1 (NEAT1)." (PMID 38566036, 2024). "Suppression of NEAT1 expression by CRISPR-Cas9 has been shown to induce the radiation-resistant cancer cell sensitivity to radiation and decrease cancer cell proliferation and the expression of stem cell markers." (PMID 37310654, 2023). "OIP5-AS1, TUG1, NEAT1, MALAT1, XIST, and TSIX were predicted to regulate cancer signaling in multiple tumor contexts." (PMID 38068923, 2023). "In conclusion, EVO can upregulate tumor-suppressor miRNAs and downregulate oncogenic lncRNA NEAT1, providing molecular mechanisms linking EVO to non-coding RNAs that can contribute, in part, to its anti-cancer activities." (PMID 37046995, 2023). "Cancer stem cells (CSCs) exhibit OXPHOS dependency and NEAT1 also functions as an inducer of CSC-like phenotypes in NSCLC." (PMID 37430270, 2023). "Key lncRNAs such as HOTAIR, NEAT1, and MALAT1 have now been discovered to drive the progression of many cancers." (PMID 37267628, 2023). "In summary, we have uncovered the m6A-associated role of VIRMA in breast tumourigenesis via the long non-coding RNA, NEAT1 and have shed light on the potential role of VIRMA in determining the fate of cancer cells under stress." (PMID 37208522, 2023). "Most of these lncRNAs were tumor-specific, although NEAT1 and MALAT1 were identified in a pan-cancer context, confirming their role in tumorigenesis." (PMID 38068923, 2023).
cancer (continued). "LncRNAs have been shown to be expressed in all major cancer types, contribute to the hallmarks of cancer, and can act as oncogenes (“onco-lncRNAs”, such as HOTAIR, NEAT1 and MALAT1) or tumor suppressors (e.g. GAS5, MEG3, NBAT and LINC-PINT)." (PMID 37346034, 2023). "There is also emerging evidence that long noncoding RNAs such as lncRNA H19, lncRNA NEAT1, lncRNA miR210HG and lncRNA DCST1-AS1 act as sponges for miR-874, suppressing miR-874 expression and contributing to cancer progression." (PMID 36323841, 2022). "NEAT1 and KCNQ1OT1 have been reported to be upregulated in a variety of cancers and promote tumorigenesis by altering the expression levels of sponged miRNAs." (PMID 36237545, 2022). "Numerous lncRNAs, such as NEAT1, UCA1, MIR22HG, and LINK-A, have involved in immune regulation in cancer." (PMID 36071454, 2022). "We finally identified 4 mRNAs (AURKA, ASNS, ESR1 and SLC39A6), 3 miRNAs (has-let-7b-5p, has-mir-10a-5p and has-mir-17-5p), and 4 lncRNAs (SNHG16, CKMT2-AS1, NEAT1 and PSMA3-AS1), all of which have been reported in cancer." (PMID 36506097, 2022). "NEAT1 downregulation can decrease CD8+ T cell death and increases cytolysis activity against cancer." (PMID 36612180, 2022). "Several lnc.RNAs, including NEAT1, LINC00473, and LINC01133 emerged to have a role in cancer carcinogenesis." (PMID 35790898, 2022). "In the following sections, we will review and highlight the characteristics and functions of some of the lncRNAs, i.e., HOTAIR, NEAT1, H19, MALAT1, and MEG3, frequently involved in several female-oriented cancers." (PMID 34885213, 2021). "Recent studies have also indicated that NEAT1 activates the WNT/β-catenin pathway through binding to EZH2 and then facilitates cancer progression." (PMID 34769497, 2021). "Resveratrol belongs to a group of natural polyphenol compounds called stilbenes, which regulate the expression of lncRNAs-PCAT29, NEAT1, MALAT1, and AK001796 and plays an essential role in cancer inhibition." (PMID 33805687, 2021). "Following the conditions of strict stringency in CLIP data and at least eight cancer types in Pan-Cancer, LRRC75A-AS1, SNHG1, NEAT1, and MIRLET7BHG were predicted to bind with miR-330-5p." (PMID 33771969, 2021). "SMAD4 and NF1, the known cancer-related genes in the CGC database, are the common ceRNAs of NEAT1 in all six CCNs." (PMID 33987091, 2021). "NEAT1 plays an oncogenic role in most types of solid tumors, and MALAT1 which is related to cancer pathophysiology are both in Cluster93." (PMID 34906173, 2021). "To evaluate the potential function of NEAT1 in AML, we first analyzed NEAT1 expression in AML along with 17 types of the most common solid tumors in the cancer genome atlas (TCGA) datasets." (PMID 34609794, 2021). "Other cancer stem cell markers such as MALAT1 and NEAT1 were upregulated in PDS‐grown cells, while expression of ETV1 was downregulated in PDS‐grown cells compared to 2D‐grown cells." (PMID 33356003, 2021). "A growing number of lncRNAs, such as MALAT1, NEAT1, and NKILA, have been shown to function as either tumor suppressors or oncogenes in various cancer types." (PMID 33869020, 2021). "From the placental dysfunction perspective, the nuclear paraspeckle assembly transcript 1 (NEAT1), abnormally upregulated in cancer, has shown increased expression in the placentas of fetal-growth-restricted fetuses." (PMID 34201957, 2021). "For example, baicalin, berberine, curcumin, and EGCG induce cell cycle arrest and apoptosis and decrease the proliferation of cancer cells by overexpression of NKLA, PAX8-AS1, CASC-2, NBR2, XIST, NEAT-1, SOX2OT-V7, respectively." (PMID 33805687, 2021). "However, as a nuclear enriched lncRNA, it should be clarified how NEAT1 sponges so many miRNAs to regulate expression of tumorigenesis-related genes, and whether NEAT1 in the peripheral blood could act as a biomarker for the diagnosis of cancers." (PMID 34512157, 2021).
cancer (continued). "Long-stranded non-coding RNAs nuclear-enriched abundant transcript 1 (NEAT1) is a pivotal component of nuclear paraspeckles, which have been reported to exert extensive roles in cancer progression." (PMID 34552925, 2021). "For example, upregulated expressions of NEAT1 and HOTAIR are responsible for therapeutic resistance in BC, OC, and various other cancer cells to chemotherapy, e.g., paclitaxel, 5-FU, cisplatin, tamoxifen, radio and endocrine therapies." (PMID 34885213, 2021). "Mechanistically, these ADV-induced GSCs upregulated lncRNA NEAT1, which is downstream to TLR9 and plays important roles in cancer stem cells likely via strengthening STAT3." (PMID 32843056, 2020). "Their host genes had been described in individual studies with regard to their roles in either PCa progression (e.g., CRIM1, NEAT1, and STIL) or other cancers (e.g., LPP and RHOBTB3)." (PMID 33105568, 2020). "The lncRNAs such as NEAT1, lincRNA‐ROR, EFNA3, and GAS5 are HSF1 targets, which are all involved in cancer." (PMID 32691951, 2020). "In cancer cells, hypoxia leads to the up-regulation of hypoxia-inducible factor (HIF), which directly alter NEAT1 expression in transcriptional regulation." (PMID 32336952, 2020). "LncRNAs NEAT1 and NEAT2 also known as MALAT1 are among the best described non-coding RNAs in human diseases and were proposed as possible targets for anti-cancer therapies." (PMID 33213097, 2020). "Nuclear paraspeckle assembly transcript 1 affects the proliferation, cell cycle progression, apoptosis, EMT, migration, and invasion of cancer cells." (PMID 32296457, 2020). "An intriguing result was the observation of the downregulation of two long non-coding RNA, which are key players in many different types of cancers, MALAT1 and NEAT1." (PMID 33193626, 2020). "Overexpression of lncRNA NEAT1 enhanced viability of cancer cells in a time-dependent manner, whereas treatment with 5-aza, an inhibitor of DNMT1, abolished the effect of NEAT1 on cell survival." (PMID 32296457, 2020). "Recently, several studies revealed that long noncoding RNA DANCR and NEAT1 promoted ROCK1-mediated signaling pathways via decoying miR-335, leading to enhancement of cancer malignancy." (PMID 32219065, 2020). "We also detected a strong reduction of XIST, NEAT1 and MALAT1, three conserved nuclear lncRNAs with well-known links to a broad range of cancer types." (PMID 32727085, 2020). "On the contrary, several studies claim that NEAT1 acts through direct interaction with specific mRNAs (e.g., ELF3) or via sponging certain miRNAs thereby promoting cancer cell growth, invasion, and migration." (PMID 32727085, 2020). "Nuclear Enriched Abundant Transcript 1 (NEAT1) is a specific structural RNA emerging as a critical component in the progress and development of cancer." (PMID 33143162, 2020). "For LSCC prognostic lncRNAs, H19, MALAT1, NEAT1, CYTOR and SNHG12 were ranked as the first five of this directly-related-to-cancer list." (PMID 32024523, 2020). "Accumulating evidence suggested that lncRNA nuclear paraspeckle assembly transcript 1 (NEAT1) expression is dysregulated in many human cancers and thus is a useful prognostic marker for cancer patients." (PMID 30894512, 2019). "when they showed that NEAT1 is a direct target of hypoxia‐inducible factor 2 (HIF‐2), which is known to be activated in cancer." (PMID 30430751, 2019). "It has been proposed that NEAT1 functions as an oncogenic lncRNA in various kinds of malignancies, such as BC, and it is suggested to induce EMT in cancer progression." (PMID 31214490, 2019). "Thus, the role of NEAT1 may differ in different cancer types." (PMID 31186635, 2019).